CD4 (CD4 molecule)
Diseases named in the same sentence as CD4 in open-access papers (continued):
Sharing a sentence is not in itself a finding about the gene and the disease.
tumor (continued). "Together, CD4+ T cells and tumouricidal myeloid cells orchestrate the induction of remote inflammatory cell death that indirectly eradicates interferon-unresponsive and MHC-deficient tumours." (PMID 37316667, 2023). "In addition, the proportion of CD8+ T cells increased in the distal, non- irradiated lymph nodes that drain the tumor while simultaneously changing CD4+ T cell ratios in the spleen." (PMID 37507972, 2023). "Promoting tumor-specific Th1 CD4 activation might be an attractive therapeutic option to enhance anti-PD-1/PD-L1 efficacy." (PMID 37516867, 2023). "Whether tumor-intrinsic parameters dictate the capacity of CD4+ CAR T cells to elicit tumor regression is unclear." (PMID 37248395, 2023). "Mice with the maximum CD4 ratio (89Zr-labeled, tumor to heart) > 9 had longer OS (P = 0.0018)." (PMID 37268978, 2023). "Furthermore, CD4+FoxP3-T (TCONV) cell characteristic genes that promote tumor migration and metastasis were enriched in tumors, while nature Treg cell characteristic genes were downregulated." (PMID 36936375, 2023). "The improved survival of human CD4+ CTLs and the potential anti-tumor effects of this population indicates CD4+ CTLs could be promising targets for immunotherapeutic strategies." (PMID 37122720, 2023). "Treg cells are FOXP3-positive CD4+ T cells strongly inhibiting anti-tumor immune responses." (PMID 36831498, 2023). "Importantly, the key parameter in this study was the location of the primary tumour, i.e., high values of CD4+ TILs were related to a better OS among oropharyngeal HNSCC (HR 0.52; 95% CI: 0.31–0.89)." (PMID 36980527, 2023). "Tumor-specific CD4+ T cell responses were dominated by tumor necrosis factor (TNF) production." (PMID 38299143, 2023). "The majority of tumor-infiltrating lymphocytes (TILs), including activated CD4+T cells, activated CD8+T cells, activated dendritic cells (DC), γδT cells, macrophages and natural killer (NK) cells were significantly enriched in cuproptosis cluster 1 and 4 compared to other clusters." (PMID 37662947, 2023). "While CD4+T-helper cells could promote anti-tumor immunity via the release of cytokines including IFN-γ." (PMID 36662756, 2023). "Another population of T cells found within the tumor microenvironment are the CD4+ T cells." (PMID 36672326, 2023). "In the tumor center, ICOSLGTCs and ICOSLGTILs were negatively correlated with CD4 and CD8." (PMID 37842091, 2023). "Additionally, the TIMER database revealed a significant correlation between TMEM150A overexpression and the levels of tumour purity, CD4+ T cells, and DCs." (PMID 38055673, 2023). "For example, the majority of infiltrating immune cells in the CRS-high group included CD8 T cells, activated CD4 memory T cells, gamma T cells, resting NK cells, activated mast cells, neutrophils, and CD4 memory T cells, which are mostly involved in anti-tumor and inflammatory response processes." (PMID 36895015, 2023). "Thus, the proportion of CD8+ Tcm (CD3+ CD8+ CD62L+ CD44+) and CD4+ Tcm (CD3+ CD4+ CD62L+ CD44+) in tumor-draining lymph nodes was measured to explore the long-term immune memory effect." (PMID 37051250, 2023). "In addition,PAIP2Bexpression was significantly associated with the tumor-infiltrating immune cells, especially T cells CD8, T cells CD4 memory resting, macrophages M0, and dendritic cells resting." (PMID 38116489, 2023). "In addition, it promoted the differentiation of anti-tumor M1 macrophages and antigen-specific CD4+ T helper 1 cells." (PMID 37509365, 2023). "Conventionally, CD4+ T lymphocytes relay tumor antigen to cytotoxic CD8+ T cells to exert antitumor effects, but the process was often hampered by regulatory T cells (Treg) consisting up to 50% of CD4+ T lymphocytes through establishing an immunosuppressive environment." (PMID 37215452, 2023).
tumor (continued). "Besides, responders had higher frequencies of CD62Llow CD8+ and CD4+ T cells, the latter containing effector and effector memory T cells crucial for the establishment of an effective and sustained anti-tumor response." (PMID 36414693, 2023). "In subsequent studies, we delineated via selective CD4+ or CD8+ T-cell depletion that CD8+ T-cells were fundamental to prevent tumor growth (potentially due to direct cytolytic activity of tumor-specific CD8+ T cells), while CD4+ T-cells played a role in shaping a potent CD8+ T-cell response." (PMID 37244905, 2023). "CD8+ and CD4+ TILs decreased in inner tumor areas (p = 0.01)." (PMID 36586079, 2023). "ESCC has been shown to harbor tumor-infiltrating Foxp3+CD4+ regulatory T cells (Tregs)." (PMID 37275884, 2023). "Tim-3+cDC2 restrained CD4+ T and attenuated the CD4+ T-driven anti-tumor response." (PMID 37771774, 2023). "Notably, irradiated tumor cells alone induced a favorable adaptive immune response, including a slight increase in pan-, effector memory-, and central memory- CD4+ and CD8+ T cells, which was significantly amplified with rWTC-MBTA." (PMID 37434263, 2023). "This polarization of CD4+ cells plays a part in tumor formation and growth." (PMID 37445860, 2023). "Depletion of CD4+ T cells even more improved the anti-tumor effect of Dox plus IL-2ic combinational treatment, presumably due to the depletion of Tregs, which could still limit IL-2 availability between the IL-2ic injections." (PMID 36705564, 2023). "B-cell activation may result in the production of tumor- specific antibodies, and B-cells can present antigens to CD4 or CD8 T-cells facilitating cellular immunity also." (PMID 37901220, 2023). "Additionally, the pulsed treatment group showed an increased number of cluster differentiation 4 (CD4+) effector memory cells compared to the single-cycle RT group, highlighting the efficacy of targeting multiple points for tumor immune evasion." (PMID 38276666, 2023). "Furthermore, CD8+ T cells, which possess powerful tumor cytotoxicity, were more efficient at proliferation compared with CD4+ T cells." (PMID 36761733, 2023). "Moreover, in tumor biopsies from the liver, CD107a degranulation marker (a surrogate marker for exocytosis in cytotoxic cells) on CD4+ CTL was significantly reduced in patients with an advanced cancer stage." (PMID 37965314, 2023). "First of all, tumor burden reduction may increase CD4 and CD8 cells, improving immunologic response to cancer." (PMID 36793604, 2023). "The antitumor effects by targeting TIM-3 may be required under certain conditions; for example, in the cases of IFN-γ-producing CD8+ and CD4+ T cells and when the ratio of tumor-infiltrating CD8+:CD4+ T cells is high." (PMID 37670328, 2023). "Overall, our study demonstrates the efficacy of ACT with NeoAg-specific CD4+ T cells in a physiologically relevant tumor model and brings new insights to the use of similar approaches for adoptive immunotherapy of human cancer to empower more diverse, potent and durable antitumor immune responses." (PMID 37400675, 2023). "Since we examined samples from human patients rather than a mouse lab model, we could not explore the mechanism through which CD4+ T cell differentiation and CD4+ CTLs involvement in tumor immunity occurred in the patients." (PMID 38077321, 2023). "Moreover, tumor with low ferroptosis score tend to be infiltrated with more CD4+ T cells, CD8+ T cells and less M1 macrophage." (PMID 35855531, 2023). "Thus, tumor vaccines prepared with new epitopes of CD4+ T cells can effectively control the development of advanced tumors." (PMID 36776837, 2023). "Apart from TAMs, Treg cells, known as the immunosuppressive class of CD4+T cells suppress anti-cancer immunity, and CAFs, which promote tumor growth, angiogenesis, invasion and metastasis and remodel extracellular matrix, were also positively associated with pdcd1lg2 expression in this study." (PMID 37006239, 2023).
tumor (continued). "Thus, we confirm previous data and extend these findings by showing that some IPdBPs are weakly recognized by both individual tumour-specific TCCs and bulk CD4+ TILs." (PMID 37198490, 2023). "On the other hand, some tumor-secreted exosomes also carry various immunosuppressive molecules, which can inhibit the proliferation of CD4+ and CD8+ T lymphocytes, or stimulate the differentiation of immunosuppressive cells, including regulatory T lymphocytes or myeloid cells." (PMID 36726489, 2023). "Whether these putative focal CNVs represent true alterations, possibly leading to the expression of truncated soluble HLA class II ectodomains by tumor cells and impairment of CD4+ T cell responses, deserve further investigation." (PMID 38318504, 2023). "The presence of CD8+ T cells expressing inhibitory markers such as LAG3, TIGIT, KLRC1, and PD-1, and FOXP3+ regulatory CD4+ T cells may prevent effective T cell–mediated tumor control in PDAC." (PMID 37751306, 2023). "However, the extent to which CD4+ T cells and B cells are involved in anti-tumor immune defense is increasingly gaining attention." (PMID 36836910, 2023). "In addition, cytotoxic CD4+ T cells can secrete granzyme B and perforin to kill the tumor cells in an HLA-II-restricted manner." (PMID 37142057, 2023). "Here, with the involvement of co-stimulatory molecules that mediate intercellular contacts and cytokine production, antigen-specific activation is carried out, inducing the activation of CD8+ T cells and polarising CD4+ T cells towards the Th1 pathway, which ultimately exerts anti-tumor functions." (PMID 37876967, 2023). "This CD4 cell cluster may represent the CD4 CTLs that mediate tumor control via direct cytotoxicity." (PMID 37185301, 2023). "Although CD4+ T cells might play a role in the anti-tumor response elicited by Lm-LLO-ISG15, as demonstrated by an increased influx of CD4+ T-cells in the TME, we found that the therapeutic efficacy of Lm-LLO-ISG15 is mainly mediated by the CD8+ T-cell." (PMID 36831577, 2023). "Moreover, a subset of CD4+ cells termed “T regulatory cells” or “Tregs” that express forkhead box protein 3 (FOXP3+) exhibit immunosuppressive activity with tumor-promoting properties." (PMID 38275375, 2023). "In various solid tumours, PD-L1 expression has been found to be related to the density of certain subtypes of ICs, including CD4+ T helper cells (Ths), CD8+ cytotoxic T cells (CTLs), FOXP3+ regulatory T cells (Tregs), and CD163+ tumour-associated macrophages (TAMs)." (PMID 38175373, 2023). "However, risk scores were negatively correlated with some recognized anti-tumor immune cells, such as activated CD4+ and CD8+ effector memory T cells." (PMID 37445803, 2023). "The elevated expression of PD-1 in the tumor CD4+ and CD8+ T cells indicates the exhausted nature of T cells in the TME, which may ultimately hinder their expansion." (PMID 37484198, 2023). "In addition to the helper functions, CD4+ T cells also exert cytotoxicity against tumor cells via Fas/FasL and perforin/granzyme pathway." (PMID 36939853, 2023). "Most MSI-H tumors predominantly align with the CMS1 category, characterized by a high mutational load, an immunogenic tumor environment, the presence of specific TILs (e.g., CD8+ cytotoxic T lymphocytes, CD4+ T helper 1 cells and natural killer cells), and an excellent prognosis in early stage CRC." (PMID 37894457, 2023). "Notably, CD4 T cells have the ability to produce significant amounts of IL-22 cytokines, which have been implicated in driving HCC progression by promoting tumor cell proliferation." (PMID 38235128, 2023). "Furthermore, CD44+PD‐1−CD127lowCD4+ T cells, referred as unexhausted cells, significantly increase in responders treated with ICB,415 demonstrating that unexhausted CD4+ T cells expand to restrain tumor progression in response to ICB treatment." (PMID 37829505, 2023).
tumor (continued). "Taken together, our results suggest that both CD4+ and CD8+ subtypes of MET-CAR-T cells can be responsible for the anti-tumor efficacy, and that CD4+ MET-CAR-T cells may elicit more robust effector T cell functions when applied to clinical settings." (PMID 37779207, 2023). "The CD4+ Trm and naïve T cells shared more significant clonotypes with other T cells, and the shared clonotypes increased with the development of infiltration in the tumour tissue, suggesting an increasing transition from CD4+ Trm cells and naïve T cells to other activated T‐cell states." (PMID 37846760, 2023). "However, this phenomenon is in accordance with the fact that tumor development demands an immunosuppressive microenvironment, in which CD4+ helper T cells, cytotoxic T cells, and regulatory cells (Tregs) are involved." (PMID 37162299, 2023). "Furthermore, expression level was higher in tumor tissues than in peritumor tissues, and the number of CD4+ T lymphocytes were significantly higher in HBV and HCV-associated HCC than in cirrhotic tissues." (PMID 37309005, 2023). "The role of CD4+ T cells in tumor control has also been directly demonstrated in clinical trials." (PMID 37649123, 2023). "Notably, tumor regression resulted from adoptive cell therapy (ACT) using endogenous tumor-infiltrating CD4+ T lymphocytes recognizing a mutant ERBB2 protein in a patient with metastatic epithelial carcinoma." (PMID 37892995, 2023). "Taken together, these results suggest that the combination of anti-PD-L1 treatments and CD4+ T cell depletion may inhibit CT26 tumor growth via the activation of CD8+ T cells and the reduction of immunosuppressive PD-L1+ immune cells." (PMID 36969495, 2023). "Similarly, understanding the mechanisms of CD4 CTL dysfunction is critical to enhancing their anti-tumor activity." (PMID 37185301, 2023). "CD4+ T-cell recognition of tumour antigen led to increased numbers of CD8+ T cells through the well-established principle of CD4+ T-cell help, whereby CD4+ T cells provide support to CD8+ T cells in the form of costimulation and cytokine production, either directly or via DCs." (PMID 37386922, 2023). "CD8+ T cells have been classically viewed as the predominant effector responsible for anti-tumor immune responses due to its direct tumor-killing feature, while CD4+ T cells function as auxiliary roles by promoting the priming and differentiation of naive CD8+ T cells." (PMID 36910622, 2023). "The expression level distribution of immune scores in clusters 1 and 2 indicated that the percentage abundance of tumor-infiltrating immune cells (T cell CD4+, endothelial cell, and T cell CD8+) was significantly decreased in cluster 1, but Macrophage and NK cell was increased." (PMID 37945610, 2023). "IFN activation of immune cells may inhibit tumor angiogenesis, whereas ILs promote the activation and growth of helper and cytotoxic T lymphocytes (CD4+ and CD8+ T cells)." (PMID 37345057, 2023). "Next to the direct effect of MCs and mediators on tumor growth, it is also possible that MCs modulate anti-tumor immunity by recruiting and activating other immune effector cells like dendritic cells, NK cells, CD8+ cytotoxic T lymphocytes, and CD4+ Th1 cells at tumor sites." (PMID 37686555, 2023). "We sought to determine whether activated CLTCH129>Q-specific CD4+ T cells could protect from live tumor challenge." (PMID 37400675, 2023). "MiR-20a-5p by targeting FGL2 and miR-139-5p by targeting STC1 could have an impact on tumor microenvironment by interacting with tumor-related inflammation and infiltration of macrophages and CD4+T cells." (PMID 38036953, 2023). "Moreover, MLN4924 leads to impaired NEDD8-dependent clearance of misfolded proteins and an altered tumor immune microenvironment due to increased numbers of cytotoxic T cells and conventional CD4+ T cells and decreased numbers of regulatory T cells." (PMID 36910623, 2023).
tumor (continued). "Our results indicated that the CD4+ CTL subset expressed PRF1, GZMA, and GZMB, indicating that CD4+ CTLs may induce apoptosis in tumor cells via the release of cytotoxic mediators, especially granzyme B and perforin." (PMID 38077321, 2023). "Although the proportion of CD4+ T cells was lower in Ccl21a-KO than WT tumors, the Treg frequency of CD4+ T cells was higher in Ccl21a-KO, suggesting that Treg accumulation was more efficiently induced in Ccl21a-KO tumor." (PMID 37664721, 2023). "CD8+T cells, NK cells, and CD4+T cells are important participants in the anti-tumor process." (PMID 36755259, 2023). "Additionally, they showed that active CD8+ T cells infiltrated the tumor tissue with an increase in CD8+:CD4+ ratio and expression of CD69 suggesting recent infiltration and cytotoxic activity." (PMID 37245011, 2023). "Intuitively, lactic acid regulates CD4+ T cell polarization and reduces the percentage of anti-tumor Th1 subpopulation by inducing silencing regulatory protein silent information regulator sirtuin 1 (SIRT1)-mediated T-box expressed in T cells (T-bet) transcription factor deacetylation." (PMID 37724112, 2023). "Physiologically, Tregs represent 4% of CD4+ cells, while they comprise 20–30% of the total CD4+ T cells in the tumor microenvironment, so they may possess a high potential as a therapeutic target." (PMID 37371612, 2023). "However, the immune system can alter the mRNA expression of an efflorescing tumor, where the immune-responsive antigenic portions of the molecule are edited or completely removed, meaning that tumors can escape recognition by CD4+ cells." (PMID 38328405, 2023). "Bengsch, Knoblock demonstrated that targeting CD25, using an anti-CD25 antibody in PDAC, reduced the number of Treg cells within the tumour and increased the number of CD4+ T helper cells, reaffirming that depleting Tregs revitalises the immune system for an anti-tumour immune response." (PMID 37190281, 2023). "In contrast to stem-cell originating cancer cells, tumor cells originating from differentiated cells expressed more robust antigen-presenting machinery and were enriched with a relatively high frequency of cytotoxic CD4+ and CD8+ T-cells." (PMID 37654482, 2023). "This could link to cancer immune evasion since tumor cells can avoid recognition by anti-tumor CD4+ T cell subsets through inhibiting MHC-II expression." (PMID 37508545, 2023). "Therefore, we investigated how the irradiation prior to CpG injection affect the OX40 expression on CD4+ T cells in tumor microenvironment." (PMID 37700338, 2023). "We sought to determine whether the help provided by the CD4+ T cell response was strictly tumor-specific." (PMID 37655661, 2023). "In a trial, low-dose multitarget TKIs, through causing durable tumor vascular normalization and intratumoral CD4+ T, CD8+ T, and NK cell infiltrations, independent of interferon γ, improved the results of anti-PD-1 therapy with fewer side effects." (PMID 38276666, 2023). "CD4+ T cells can directly kill the tumor cells by producing a high level of IFN-γ." (PMID 37426671, 2023). "Similarly, after excluding the effect of operation time, tumor stage as well as tumor location by multivariate logistic regression analysis, the effect of types of surgery on patients’ postoperative CD4+T and CD8+T remained statistically significant." (PMID 36983320, 2023). "Additionally, steatohepatitis was noted to reduce the ability of immunotherapeutic agents thereby inhibiting hepatic tumor growth through reduction of tumor infiltration by CD4+ T cells and effector memory cells." (PMID 37608898, 2023). "Previous studies revealed that CDK1 which could induce tumor proliferation was also positively correlated with CD4+ T-cells and CD8+ T-cells in HCC." (PMID 37313428, 2023). "To determine whether the acceleration of tumor growth in HFD-fed mice is involved in the reduction of CD4+ T cells, we performed a depletion analysis according to a previous report." (PMID 36611881, 2022).